XPNPEP1 (X-prolyl aminopeptidase 1)
Description:
Metalloaminopeptidase that catalyzes the removal of a penultimate prolyl residue from the N-termini of peptides, such as Arg-Pro-Pro. Contributes to the degradation of bradykinin.
Synonyms: sAmp; XPNPEPL; XPNPEPL1; APP1; XPNPEP
Tractability: Small molecule: a drug acting on it is in phase 2 or 3 trials. PROTAC: ubiquitination databases record sites on it; its protein half-life has been measured; a small molecule that binds it is known.
Target class: Metallo protease MG clan; Metallo protease M24B subfamily; Enzyme; Protease; Metallo protease
Gene: Protein-coding gene on chromosome 10 (109,864,494 to 109,923,553, reverse strand). Ensembl gene ENSG00000108039.
Subcellular location: Cytoplasm, cytosol
Subcellular location (Human Protein Atlas): Cytosol
Gene Ontology:
Molecular function: aminopeptidase activity; manganese ion binding; metalloaminopeptidase activity; protein homodimerization activity
Biological process: bradykinin catabolic process; negative regulation of programmed cell death; proteolysis
Cellular component: cytosol; extracellular exosome; cytoplasm
Genetic constraint (gnomAD): Loss-of-function variants: 35 observed, 85.17 expected, observed/expected ratio (o/e) 0.41, 90% interval 0.31 to 0.55. The upper end of that interval is the gene's LOEUF score, 0.55, which puts it in group 2 of 6, group 1 being the genes least tolerant of losing a copy. Missense variants: 580 observed, 797.92 expected, observed/expected ratio (o/e) 0.73, 90% interval 0.68 to 0.78. Synonymous variants: 264 observed, 280.19 expected, observed/expected ratio (o/e) 0.94, 90% interval 0.85 to 1.04.
Homologues: Orthologues: macaque XPNPEP1 (98% identical), chimpanzee XPNPEP1 (97% identical), guinea pig XPNPEP1 (95% identical), rat Xpnpep1 (95% identical), pig XPNPEP1 (94% identical), dog XPNPEP1 (94% identical), mouse Xpnpep1 (90% identical), rabbit XPNPEP1 (86% identical), zebrafish xpnpep1 (69% identical), Drosophila melanogaster ApepP (45% identical), Caenorhabditis elegans app-1 (38% identical), Caenorhabditis elegans pid-5 (32% identical). Paralogues in human: XPNPEP2 (39% identical), XPNPEP3 (14% identical), PEPD (13% identical), METAP1D (11% identical), METAP2 (10% identical), METAP1 (10% identical), PA2G4 (7% identical).
Diseases named in the same sentence as XPNPEP1 in open-access papers:
XPNPEP1 is named in the same sentence as 45 diseases in open-access papers, as found by Europe PMC text mining. Sharing a sentence is not in itself a finding about the gene and the disease. The quoted sentences say what the papers report.
multiple myeloma (3 papers, 2021 to 2023). "PNPEP1 (aminopeptidase P) is specifically expressed in lung tumors and presented in pulmonary blood vessels, and high expression of XPNPEP1 in multiple myeloma plasma cells has been associated with decreased overall survival." (PMID 37576511, 2023). "A higher expression of the aminopeptidase genes XPNPEP1, RNPEP, DPP3, and BLMH in multiple myeloma plasma cells was associated with shorter patient overall survival." (PMID 33810334, 2021).
cognitive disorder (2 papers, 2022). A disease affects cognitive processes. "Some migration-associated mutations were found in other brain activity genes involved in sleep and cognitive disorders in mice and humans (prominently XPNPEP1 and PAK3)." (PMID 35143486, 2022). "We reasoned that if exaggerated NMDAR signaling is a key mechanism in triggering hyperactivity and cognitive disorders, the suppression of NMDAR activity will reverse the behavioral and cognitive symptoms observed in adult Xpnpep1–/– mice." (PMID 35922532, 2022).
asthma (1 paper, 2014). "Lastly, in the Asthma BRIDGE replication population, we evaluated the relation between DNA methylation and expression for XPNPEP1, PPEF2, and FRMD4 as well as the association between IUS and expression." (PMID 24964093, 2014). "XPNPEP1 and PPEF2 are two genes that may also be of interest as they were significant in both the CAMP and Asthma BRIDGE populations." (PMID 24964093, 2014).
atherosclerosis (1 paper, 2022). A disease characterized by the build-up of fatty material and calcium deposition in the arterial wall resulting in partial or complete occlusion of the arterial lumen. "We speculate that the XPNPEP1 gene indirectly affects the occurrence and development of atherosclerosis by participating in the function and metabolic mechanism of vascular endothelial cells." (PMID 36339005, 2022).
cognitive (1 paper, 2022). "As chronic memantine treatment reversed neurodegeneration in the hippocampi of Xpnpep1–/– mice, we investigated whether the behavioral and cognitive deficits in Xpnpep1–/– mice were reversed by chronic memantine treatment." (PMID 35922532, 2022).
developmental delay (1 paper, 2022). "Intriguingly, repeated administration (twice daily) of memantine (10 mg/kg, i.p.)for five weeks ameliorated the developmental delay observed in Xpnpep1–/– mice." (PMID 35922532, 2022).
epilepsy (1 paper, 2021). A brain disorder characterized by episodes of abnormally increased neuronal discharge resulting in transient episodes of sensory or motor neurological dysfunction, or psychic dysfunction. "We found that aminopeptidase P1 is predominantly expressed in neurons, and genetic ablation of Xpnpep1 resulted in enhanced neuronal excitability in CA3b pyramidal neurons, which may account for neurodegeneration and epilepsy in Xpnpep1−/− mice." (PMID 33441619, 2021).
fluorosis (1 paper, 2023). "The top 10 drugs have been reported in previous studies, namely Celastrol, LDN-193189, XPNPEP1, GNB5, Importazole, LDHB, NUAK1, IFNG, IFNB1, and YWHAH, suggesting that these drugs may be effective candidate drugs for the treatment of fluorosis." (PMID 36835629, 2023).
latent infection (1 paper, 2023). "On the other hand, the expression of lncRNAs lnc-XPNPEP1-5, lnc-CASKIN2-2, lnc-HSPA13-6, lnc-CLIC5-1, and LINC02502 was significantly reduced in both the latent infection group and the TB patient group compared to the uninfected HC group (all P-values < 0.05)." (PMID 38156018, 2023). "Furthermore, we found that lnc-XPNPEP1-5, lnc-CASKIN2-2, lnc-HSPA13-6, lnc-CLIC5-1, and LINC02502 were significantly downregulated in TB-infected patients, while LINC00528, lnc-SLC45A4-3, and LINC00926 were significantly upregulated in TB patients and latent infections." (PMID 38156018, 2023).
lung adenocarcinoma (1 paper, 2023). A carcinoma that arises from the lung and is characterized by the presence of malignant glandular epithelial cells. "To further evaluate the impact of hypoxia-related genes on lung adenocarcinoma cells, we conducted RT-PCR and in vitro experiments, focusing on the expression of SLC2A1 and XPNPEP1 genes which promote the proliferation of lung adenocarcinoma cells." (PMID 37576511, 2023). "The amplified products were subjected to agarose gel electrophoresis, and six samples all gave clear bands in the correct region indicated by the marker, confirming that the six predicted six-HRGs (STC1, PFKL, HK1, PDK3, SLC2A1, XPNPEP1) were all expressed in lung adenocarcinoma A549 cells." (PMID 37576511, 2023). "Knock-down of SLC2A1 or XPNPEP1 substantially suppressed the proliferation and migration of A549 cells, demonstrating that the expression of these genes promotes the proliferation of lung adenocarcinoma tumors." (PMID 37576511, 2023).
microcephaly (1 paper, 2022). A congenital or acquired developmental disorder in which the circumference of the head is smaller than normal for the person's age and sex. "Unexpectedly, chronic memantine treatment improved microcephaly in Xpnpep1–/– mice." (PMID 35922532, 2022).
thyroid neoplasms (1 paper, 2021). "Both XPNPEP1 and RNPEP enzyme activities were found to be significantly elevated in thyroid neoplasms when compared with nonmalignant adjacent tissues." (PMID 33810334, 2021).
tumor (4 papers, 2019 to 2022). "All except two of these shared variants (BRAF hotspot V600E in sync_4 and XPNPEP1 R204H in sync_11 (tumours sync_11–2 and sync_11–3)) were frameshift mutations." (PMID 30894686, 2019).
XPNPEP1 also shares sentences with these, for which no sentence is quoted: cancer (4 papers); osteoporosis (3); amyloidosis (2); degenerative diseases (2); lung carcinoma (2); adenoma (1); aging (1); alopecia (1); Brain atrophy (1); cardiomyopathy (1); cataract (1); cerebral palsy (1); clear cell renal cell carcinoma (1); colorectal tumors (1); Crohn disease (1); Dejerine-Sottas syndrome (1); dementia (1); diabetes (1); dilated cardiomyopathy (1); histiocytic sarcoma (1); ileitis (1); immune dysfunction (1); inflammation (1); lupus nephritis (1); myocarditis (1); myofibrillar myopathy (1); neurological diseases (1); Ovarian cyst (1); sarcopenia (1); scoliosis (1).
A further 2 diseases each share a sentence with XPNPEP1 in 1 paper.